MIR874 (microRNA 874)
Synonyms: hsa-mir-874; MIRN874; mir-874
Gene: MicroRNA gene on chromosome 5 (137,647,572 to 137,647,649, reverse strand). Ensembl gene ENSG00000216009.
Gene Ontology:
Biological process: miRNA-mediated post-transcriptional gene silencing
Cellular component: RISC complex
Homologues: Orthologues: chimpanzee ptr-mir-874 (100% identical), dog MIR874 (100% identical), pig ssc-mir-874 (100% identical), macaque mml-mir-874 (99% identical), rat Mir874 (97% identical), guinea pig MIR874 (96% identical), mouse Mir874 (96% identical), rabbit MIR874 (76% identical).